CCR2 (C-C motif chemokine receptor 2)
Diseases named in the same sentence as CCR2 in open-access papers (continued):
Sharing a sentence is not in itself a finding about the gene and the disease.
infection (continued). "However, starting at 24 hours post infection, a significant increase in bacterial burden (3.7-fold in BALF and 3.6-fold difference in lung; p<0.001) was observed in CCR2-depleted mice compared to WT mice." (PMID 39418302, 2024). "On day 1 post infection, α-CCR2 treated mice lost comparable weight as isotype controls, but on day 2 post infection they began to recover unlike the isotype mice." (PMID 39127259, 2024). "Monocyte egress from the BM is dependent on CCR2, a receptor for CCL2, during infection." (PMID 39040105, 2024). "While both Ly6CHi and Ly6CLo blood monocytes have demonstrated similar phagocytic capacity, only the Ly6CHi subset expressed high levels of CCR2 and CD62L and are thus theorized to play an inflammatory role when they are recruited to sites of infection, which is consistent with MPO expression." (PMID 35897821, 2022). "Notably, we found that the expression of specific markers of M1 type microglia (Aif1, Cd86, Cd40, Ccl2, Ccr2, Cx3cr1, IL-1β, IL-6, and NOS2) was elevated post infection." (PMID 36618398, 2022). "We then tested whether CCR2 is necessary for pre-cDC localisation at infection foci by measuring co-localisation between pre-cDC surfaces (eGFP+ MHC-II- CD64- B220-) and IAV-infection foci (M+ NP+) in Clec9aWTCCR2 versus Clec9aΔCCR2 lung slices." (PMID 34739343, 2021). "While we did not monitor neutrophil dynamics here, neutrophils are well known to be massively recruited and undergo activation in infected spleens, and we and others have previously shown that they cluster with CCR2+Ly6C+ monocytes and CD8+ TM cells at infection foci." (PMID 34516896, 2021). "SARS‐CoV‐2 may primarily infect monocyte and CD14+ subsets with higher expressions of CCR2 and CX3CR1 which may differentiate and migrate from the periphery to the target sites as macrophages during infection." (PMID 34363351, 2021). "For example, monocyte subset expression of CCR2 and CX3CR1 is altered in infection." (PMID 33717107, 2021). "In contrast, in the course of studying the role of MIG/CXCL9 during LVS infections, we found that CCR2 KO mice did not survive lower doses of ID LVS infection that were sublethal for wild type mice." (PMID 33760886, 2021). "Contrarily to these intracellular pathogens, our data show that Orientia is unique in that CCR2 was not required to confer protection in our intradermal infection model." (PMID 34290699, 2021). "To verify that macrophages confer enhanced protection in Lyz2-DP1−/− mice, we blocked macrophage infiltration into the infected brain by treating mice with CCR2-blocking (MC21 monoclonal antibody [mAb]) or control antibody 1 day before and 3 and 7 days after infection." (PMID 34488442, 2021). "At 1–3 months after infection, levels of CCR2 were lower on intermediate and non-classical monocyte populations, implying that cells with the highest levels of CCR2 emigrated from the circulation." (PMID 34835045, 2021). "Another study compared responses of C57BL/6J and CCR2 KO mice to an IV dose of 2 x 104 LVS, but most studies were performed using mice infected for only 24 hours, well before morbidity develops from LVS infection." (PMID 33760886, 2021). "We showed that clearance of O. tsutsugamushi was significantly less effective and delayed in the absence of CCR2 in the lung (and also liver), but CCR2-/- mice were eventually able to reduce the infection." (PMID 34290699, 2021). "The radical change in CCR2 from a high to a medium level did not allow Th2 to come to the site of the infection." (PMID 35096290, 2021). "In the absence of CCR2, monocytes are retained in the bone marrow during homeostatic conditions and cannot migrate to the site of inflammation during infection or inflammation." (PMID 33664739, 2020). "Independent of infection, CCR2 expression by Ly6Chi monocytes in the blood and liver of gonadectomized and testosterone-supplemented male mice was lower than that in the gonadectomized control group." (PMID 32651360, 2020).
infection (continued). "Through signalling via CCR2 and CCR4 receptors, CCL2 mediates chemotaxis of monocytes and dendritic cells, as well as memory T cells to the sites of inflammation upon tissue injury or infection." (PMID 32295518, 2020). "In contrast to Ly6Chi monocytes whose recruitment was dramatically reduced in the absence of CCR2 signaling, Ly6Clow monocyte recruitment was not affected 24 h post infection and only slightly affected 48 h post infection." (PMID 32101593, 2020). "Overall, these results suggest that ITC are prepared to buffer ROS at baseline, a useful adaptation for effector cells expressing chemokine receptors, such as CCR1, CCR2, and CCR5 that direct them to the same sites of infection or inflammation as monocytes and neutrophils." (PMID 30737409, 2019). "Such macrophages/monocytes are unable to secrete protective concentrations of proinflammatory chemokines and cytokines (e.g. TNFA, CCR2 or IL6) at the site of infection in an attempt to attract lymphocytes during immune restoration, thus become more permissive to infection relapse." (PMID 32905461, 2019). "Since the CCR2-V64I mutation tracks, through linkage disequilibrium, with mutations in the promoter region of CCR5, population-specific patterns of CCR2 and CCR5 haplotypes may also explain disparities in infection or disease progression." (PMID 31377844, 2019). "We then wished to determine if there was a requirement for CCR2 to maintain viral-specific T cells within adipose tissue given the lack of central memory and memory precursors through f.p. infection." (PMID 31220189, 2019). "We found that Ccr2 KO mice that received Ly6Chi monocytes from WT mice displayed lower kidney fungal burden than mice that received Ly6Chi monocytes from TKO1 mice, 72 h post-infection." (PMID 31242262, 2019). "To test the potential contributions of CCR2+ monocytes and their derivative cells to host-mediated defense against infection with the fbp1Δ mutant, we employed the CCR2-DTR mouse strain, which permits the temporal removal of CCR2+ cells upon diphtheria toxin (DT) administration." (PMID 29317510, 2018). "This subset induces a minimal level of respiratory burst and is unresponsive at early stages of infection due to the lack of chemokine receptors (CCR2) necessary for the migration of this subset to the infection site." (PMID 30105020, 2018). "In contrast, CCR2-DTR → Irf3-/-;Irf7-/- mice treated with PBS were protected against severe RRV disease, indicating that IRF3 and IRF7 sufficient hematopoietic cells can protect Irf3-/-;Irf7-/- mice against RRV-T48-nsP16M infection." (PMID 29244871, 2017). "Transfer of WT γδT17 cells reduced nasopharyngeal bacterial burden by ∼10-fold, whereas Ccr2−/− γδT17 cells completely failed to control infection." (PMID 28580944, 2017). "Critically, Ccr2-/- mice had significantly higher bacterial burdens in the lung at 48 and 96 hours post-infection, demonstrating that Ly6Chi monocytes play a key non-redundant role in host defense against L. pneumophila." (PMID 28384349, 2017). "The decreased number of IFNγ+ γδ T cells in Ccr2-/- mice was not due to a defect in the total number of γδ T cells, as Ccr2-/- and B6 mice had equivalent numbers of lung γδ T cells during infection." (PMID 28384349, 2017). "Levels of «Ly6Chi» monocytes also increased on day 6 p.i. in CCR2-/- (from 1.0%±0.1 prior to infection to 5.9%±1.7; P<0.001 (not indicated)) and CCR2-/-→WT (from 1.3%±0.5 to 3.8%±1.0; P<0.05 (not indicated))." (PMID 27930721, 2016). "In contrast, injection of anti-CCR2 mAb during an already ongoing infection barely influenced developing pathology and did not protect against ECM-related death (Fig 2Ec." (PMID 25884830, 2015). "Moreover, by 48 h after infection CXCL1 levels and neutrophil recruitment to the lung is unaffected in CCR2-depleter mice, thus suggesting that distinct mechanisms of neutrophil recruitment are operational at various times after infection." (PMID 25629406, 2015).
infection (continued). "Coinfected CCR2−/− mice lacking inflammatory monocytes and related populations have reduced lung damage prior to secondary infection, control bacterial outgrowth and thus are protected." (PMID 26265006, 2015). "Although CCR2−/− mice have diminished levels of circulating Ly6Chi monocytes, they have increased numbers in the bone marrow at rest, and large numbers of activated TNF-α producing Ly6Chi monocytes accumulate in the bone marrow during infection." (PMID 24945711, 2014). "We find that CCR2+Mo and their derivative dendritic cells (Mo-DCs) are required for defense against IA and that mice lacking these cells succumb to infection with A.fumigatus." (PMID 24586155, 2014). "CCR2−/− mice (on a C57BL/6 background) were resistant to a high-level infection with T. muris (not shown)." (PMID 25261482, 2014). "This response was found to be entirely dependent on CCR2, since Ccr2-/- mice showed no increase in monocyte levels in the blood throughout the course of infection." (PMID 25324719, 2014). "Therefore, we first checked the proportions of Gr1 + CD11b + cells and CCR2+ inflammatory monocytes in the PBMC and BM during infection." (PMID 25407417, 2014). "Immunohistochemical staining for F4/80 revealed that, in the absence of infection, Mφs resided in the lamina propria of the colon in both CCR2−/− mice and their WT controls." (PMID 25261482, 2014). "As suggested by the retention of these cells in the BM in Ccr2-null mice, no increase in infection-induced early myeloid progenitor subsets in the spleen was recorded in these mice upon infection with P. chabaudi." (PMID 23762028, 2013). "In Ccr2-null mice we found a clear dissociation between IFN-γ signaling in the BM as evident by the infection-induced changes in their phenotype but without any contraction in the numbers of myeloid-restricted early progenitors." (PMID 23762028, 2013). "C57BL/6 CCR2 −/− mice were infected with K. rhinoscleromatis and the bacterial load and the presence of inflammatory monocytes/Mikulicz cells assessed by FACS and histology 1, 3 and 5 days post-infection." (PMID 23554169, 2013). "Mice lacking CCL2 or CCR2 exhibit diminished inflammatory monocyte recruitment to infection sites resulting in enhanced bacterial growth and overwhelming infection." (PMID 22629382, 2012). "Earlier studies have shown that during L. monocytogenes and influenza virus infection, TNF-α/inducible nitric oxide synthase (iNOS)-producing (Tip) DCs failed to accumulate at the site of infection in CCR2−/− mice." (PMID 23272202, 2012). "Systemic infection of mice with L. monocytogenes leads to recruitment of CCR2+ monocytes via CCL2, into the spleen where they differentiate into TNF- and inducible NO synthase (iNOS)-producing DCs that are essential for control of the infection." (PMID 22383883, 2012). "There were no changes in the percentages of CD16 positive and CD16 negative, or CCR2 positive and CCR2 negative monocyte subpopulations observed following infection with Udorn." (PMID 22238612, 2012). "Surviving CCR2–/–mice have normal blood parameters at later stages (day 14) of infection (data not shown)." (PMID 21206747, 2010). "Next, blocking of MCP-1 with neutralizing antibodies for 30 min before infection also down-regulated CCR2 compared to no antibody controls using fluorescent microscopy." (PMID 19305493, 2009). "Unlike CCR2 and CCR5 deficient mice, 40% of infected CCR1 deficient mice succumbed to infection by 7 dpi." (PMID 19079579, 2008). "However, mononuclear phagocyte recruitment is not completely abrogated in the absence of CCR2, indicating that one or more other chemoattractant receptors contribute to this response to infection." (PMID 40497732, 2025). "However, patients who developed post-operative infections had lower levels of CCR2 expression pre- and post-operatively compared to patients without post-operative infections." (PMID 38655251, 2024). "Without CCR2, bacteria disseminated and the mice succumbed to the infection." (PMID 38352492, 2024).
infection (continued). "While mutant SFTS viruses lacking N-linked glycosylation of GP showed negligible usage of C-type lectins in infection and reduced virulence in a murine model (the present study), it is not yet addressed whether the mutant viruses use CCR2." (PMID 39008518, 2024). "Therefore, differences in CCR2, and CCL2 and CCL7 upon infection might explain the delay recruitment of inflammatory monocytes." (PMID 38578798, 2024). "Next, we examined whether CCR2 plays an integral role in controlling and maintaining normal pregnancy in the absence of infection." (PMID 39051675, 2024). "Upon infection, chemoattractants such as CXCL1, CXCL2 and IL-17 are produced in the lung, leading to further neutrophil recruitment and transmigration into the tissue, a process that is highly dependent on C-C chemokine receptor type 2 (CCR2)-positive blood monocytes." (PMID 37566060, 2023). "Indeed, CCR2+ monocytes can be immunosuppressive, they replenish important macrophage populations, and they play pivotal roles during infection, potentially explaining the lack of positive results following a CCR2 therapeutic blockade in MS." (PMID 33679799, 2021). "Thus, Ag presentation by splenic CCR2+Ly6C+ monocytes is not required for Ag-dependent CD8+ TM cell activation during recall infection." (PMID 34516896, 2021). "As a limitation to this study, we cannot exclude that other inoculation routes (e.g. i.v.), higher infection doses or infections in male mice – male mice express higher levels of CCR2 than females in non-classical splenic monocytes – would produce a different phenotype." (PMID 34290699, 2021). "We speculated that immune memory would be prolonged in Ccr2-/- mice, in which monocyte input after infection is largely absent." (PMID 32639232, 2020). "Thus, preclinical TB studies indicate that T1-IFNs stimulate the influx of CCR2+ monocytes, but not PMN, to the site of infection in a CCR2-dependent way via the induction of CCL2 in parenchymal cells." (PMID 28424682, 2017). "Though a subset of NK cells express CCR2, we did not observe a defect in NK cell recruitment to the lung, as B6 mice and Ccr2-/- mice had similar total numbers of lung NK cells during infection." (PMID 28384349, 2017). "Finally, we demonstrate that the emergence of these Ly6c+ MO-DCs in the CNS is dependent on CCR5 and, surprisingly, independent of CCR2, which is classically involved in inflammatory monocytes recruitment to lymphoid organs and to other sites of infection." (PMID 27808089, 2016). "No immuno-reactivity for CCR2 could be detected prior to infection in all groups of mice (data not shown)." (PMID 27930721, 2016). "Thirteen weeks after infection, we observed that the population of human peripheral blood cells that expressed the canonical human dendritic cell markers CD11c and HLA-DR (MHC II) in conjunction with PDL1 also expressed the monocyte markers FcγRI and CCR2 and iregDC markers CD39 and CD95." (PMID 26808628, 2016). "In addition, B. dermatitidis DppIVA, which is a multifunctional protein that can act as a serine protease, assists in evasion of the host immune response during infection by cleaving CCL7, a C-C chemokine signal, which recruits Ly6Chi CCR2+ monocytes to the sites of infection." (PMID 27896220, 2016). "In addition, the lack of CCR2 results in increased mortality and impaired leukocytes activation following infection of the CNS with a neurotropic coronavirus." (PMID 27930721, 2016). "Propofol did not reduce the recruitment of CCR2+Ly-6C+ mononuclear phagocytes to the spleen following bacterial infection or alter the number of differentiated F4/80+CD80+MHC-II+ mononuclear phagocytes at 24 hours post-infection." (PMID 26381144, 2015). "To evaluate the relative contribution of CCR2-dependent and Flt3L-dependent migratory DC subsets in T cell priming during OPC in vivo, we examined the induction of C. albicans-specific Th17 cell in the cervical lymph nodes of OPC infected Flt3l-/- and Ccr2-/- mice on day 7 post-infection." (PMID 26431538, 2015).